CD4 (CD4 molecule)
Diseases named in the same sentence as CD4 in open-access papers (continued):
Sharing a sentence is not in itself a finding about the gene and the disease.
lymphopenia (continued). "Most of the patients in our study presented with neutrophilia and lymphopenia on admission; specifically, reduced CD3+, CD4+, and CD8+ T-cell counts were observed in some patients." (PMID 32645044, 2020). "We found a remarkable correspondence between the in vitro ADCC mediated lysis of CD4 T-cells by plasma of some patients with ALPS-FAS and in vivo CD4 lymphopenia." (PMID 31191551, 2019). "Lymphopenia occurred in all patients (grade 3/4 in 46 patients [96%]), with all evaluated lymphocyte subsets (CD3+, CD4+, CD8+, CD16+, CD20+, CD56+) showing reductions from baseline." (PMID 29974231, 2019). "The patient's initial immune evaluation as a newborn revealed lymphopenia including reduced numbers of CD19+ B cells, CD3+, CD4+, and CD8+ T cells." (PMID 31921190, 2019). "Lymphopenia was present in hSTING-N154S peripheral blood, with decreases in CD19+, CD4+, and CD8+ cells as compared with littermate controls." (PMID 31221625, 2019). "Ultra-high dose rate was equally potent in depleting CD3, CD4, CD8, and CD19 lymphocyte populations in both cardiac and splenic irradiation models of lymphopenia." (PMID 31748640, 2019). "Low total lymphocyte counts were found in 47 patients (45.2%), and the most frequency lymphopenias were CD19+ B-cell (57.7%), CD3+ (40.4%), and CD4+ (36.5%)." (PMID 29963040, 2018). "Immunological work up performed at the time revealed normal immunoglobulin levels, with CD4+ and CD8+ lymphopenia." (PMID 30038614, 2018). "Screening identified leucopenia, lymphopenia, low CD3 and CD4 levels, and undetectable immunoglobulins." (PMID 30305145, 2018). "In summary, we demonstrate that CD4+ T cells and CD19+ B cells are comparably decreased in all fingolimod treated patients whereas grade of lymphopenia is primarily defined by individual variation of CD8+ T cell and NK cells." (PMID 30524432, 2018). "In this study, we established that significant CD3, CD4, CD8, CD19, and CD56 lymphopenia occurs in patients with CPA." (PMID 29371544, 2017). "Second, with the exception of CD4 counts, it is difficult to establish precise levels of clinically significant CD3, CD8, CD19, and CD56 lymphopenia." (PMID 29371544, 2017). "This trauma-induced lymphopenia was comprehensive with reduced numbers of CD56DIM and CD56BRIGHT NK cells, TEMRA CD4+ and CD8+ T cells, and both naive and effector memory CD4+ T cells." (PMID 28719602, 2017). "As a result, both CD4+ and CD8+ T cell counts were drastically reduced upon RMD administration (respectively), but similar to the overall lymphopenia, they rebounded to pretreatment levels within one week." (PMID 27632364, 2016). "She showed lymphopenia and her lowest counts of CD3+, CD4+, CD8+, and CD25+ lymphocyte subpopulations, and CD4+/CD8+ ratio during the whole study." (PMID 27829434, 2016). "The lymphopenia involved both CD4+ and CD8+ cells, with an expansion of tumorigenic CD4+ and CD8+ activated CD44+ CD62L− memory cells." (PMID 27725924, 2016). "In analysing the levels of lymphocyte populations in our patients, we observed that the levels of CD4 and CD8 were maintained stable despite the high percentage of lymphocytopenia recorded (58.1%) and, as such, a response to T.SPOT.TB was possible." (PMID 25009813, 2014). "In the present manuscript, we show that IL-7 in vitro or lymphopenia in vivo can upregulate the total levels of STAT1, -2 and -3, rendering CD4 T cells more sensitive to IFN-α." (PMID 24603698, 2014). "In a murine model, lymphopenia and chronic treatment with IFN-α led to diminished survival of CD4 T cells and an expansion of CD8 T cells, thus recapitulating the alterations of the homeostasis of these pools observed in patients with HIV infection." (PMID 24603698, 2014). "Lymphopenia-induced HSP involves both slowly and rapidly proliferating CD4+ T cells: the former remain phenotypically naïve, whereas the latter convert from a naïve to a memory-like phenotype with a greater activation potential." (PMID 23301078, 2013).
lymphopenia (continued). "This lymphopenia is due to several combined effects: destruction of HIV-infected cells, increased cell death of uninfected CD4+ T cells, and impair renewal." (PMID 23243424, 2012). "All patients with MST1 deficiency have a similar immunological phenotype, characterized by naive CD4+ and CD8+ T-cell lymphopenia in particular." (PMID 22952854, 2012). "NK, CD4 and CD8 lymphopenia developed in 100%, 90% and 60% of severe cases versus 13% (p<0.001), 28%, (p = 0.001) and 18% (p = 0.014) of mild cases." (PMID 22363665, 2012). "NK-cell lymphopenia was part of the severe and global lymphopenia that occurred in ICU patients, and involved B cells (CD19+) and T cells (CD3+CD4+ and CD3+CD8+)." (PMID 23236375, 2012). "There was severe CD4 (P < .001) and CD8 (P < .01) lymphopenia and upregulation of costimulatory molecule CD30 on CD4 and CD8 T cells (P < .05); this increase was higher in relapsing tuberculosis." (PMID 22567259, 2010). "In this model, lymphopenia induced the proliferation and differentiation of both potentially autoreactive CD8+ as well as CD4+ T cells into memory-like cells." (PMID 20856822, 2010). "This study provides the first report of frequent and severe CD4, CD8, and CD19 lymphopenia in sarcoidosis patients to our knowledge." (PMID 20140091, 2010). "In patients presenting with lymphopenia and low systemic inflammation, those who received corticosteroids had higher observed survival than those who did not (CD4+‐depleted subgroup: 84.4% vs." (PMID 41492360, 2026). "A reduction in CD3+ T cells, CD4+ T cells, and CD8+ T cells indicate suppressed immune function, and abnormalities in immune function (e.g., lymphopenia) alongside an imbalance of inflammatory factors have been suggested to play a significant role in the development of sepsis." (PMID 40642098, 2025). "Whilst this suggests that reduced IL-2 and its receptor may be preventing CD4+ proliferation and differentiation, therefore increasing the risk of post-operative infections, administration of therapeutic IL-2 following surgery did not prevent the initial lymphopenia." (PMID 41148718, 2025). "Indeed, RAG1 R972Q and R972W mutant mice had similar levels of CD4+ and CD8+ T cell lymphopenia in spleen, compared to STING GOF mice (Fig. EV7A)." (PMID 40804163, 2025). "CD4+, CD8+ and NK-cell monitoring and development of persistent lymphopenia." (PMID 41439928, 2025). "Prior studies on the effect of CRT on peripheral lymphocytes are consistent with this finding in patients without HIV, demonstrating that women receiving treatment typically undergo a significant decrease in peripheral CD4 frequency and CD4:CD8 ratio, resulting in prolonged clinical lymphocytopenia." (PMID 40099965, 2025). "Although naïve T cell lymphopenia has been described, and CD3+ lymphopenia has been reported following immunosuppressive therapy, this specific CD4+ T cell defect has not been previously documented." (PMID 40977713, 2025). "The assessment of lymphocyte subpopulations could help in ruling out severe CD3+, CD4+, or CD8+ lymphocytopenia before the administration of live vaccines." (PMID 40333279, 2025). "Several groups noted that CD4+ and CD8+ T-cell lymphopenia developed progressively." (PMID 41298860, 2025). "The reduced frequency of CD4+ and CD8+ T-cell subsets and phenotypes during uncomplicated malaria and 4 weeks postrecovery compared to community controls may be due to lymphopenia." (PMID 41285032, 2025). "All seven patients were diagnosed with CAPA without neutropenia, four with lymphopenia, seven with decreased CD4+ T lymphocyte, and five with decreased CD8+ T lymphocyte." (PMID 39865524, 2025). "Our recommendation includes routine monitoring of CD4 counts by flow cytometry in patients on long-term use of fingolimod therapy (at least five years), even without lymphopenia." (PMID 39512980, 2024).
lymphopenia (continued). "In summary, this index case presented with severe combined immunodeficiency (SCID) of unknown genetic etiology, with profound CD4 and CD8 naïve T cell lymphopenia alongside an ectodermal phenotype." (PMID 39270020, 2024). "In fact, both CD4+ and CD8+ populations in spleen and lymph nodes contain increased levels of of memory T cells in the cKO compared to the control, indicating a potential compensatory effect due to T cell lymphopenia." (PMID 39308865, 2024). "In the majority of studies, elevated Treg fractions were documented among peripheral blood CD4+ T cells of patients with glioblastoma, even in cases with severe CD4+ T cell lymphopenia (<200 cells/μL) and regardless of steroid use." (PMID 38481999, 2024). "Serial immunologic tests of the patient revealed a progressive complex profile of inborn errors of immunity, which encompasses a slight decline in the count of white blood cells (WBC), accompanied by lymphopenia, below-average levels of CD3 and CD4 cells, and abnormalities in B cell indices." (PMID 38350907, 2024). "Despite lymphopenia with a reduced CD4 count, his symptoms resolved, and an RNA PCR test did not detect any presence of HIV (False +)." (PMID 38304642, 2024). "Lymphocyte immunophenotyping did not reveal any imbalance between CD4 and CD8 sub-populations, B lymphopenia, and natural killer (NK) deficiency." (PMID 39139787, 2024). "Acute SARS-CoV-2 infection was characterised by T cell lymphopenia, and a reduction in NK cells and naïve CD4 and CD8 cells, without any significant differences between immunosuppressed and non-immunosuppressed patient groups." (PMID 38791279, 2024). "The ATO assay demonstrated that the patient’s T cell precursors were capable of fully differentiating ex vivo into single positive CD4 and CD8 T cells suggesting that CTTI may provide definitive treatment for her T cell lymphopenia." (PMID 39364398, 2024). "This leads to defective calcium homeostasis, mitochondrial malfunction, CD4+ lymphopenia, a quasi-absence of naïve CD4+ and CD8+ cells, an increase in memory cells, and a distinct TCR repertoire." (PMID 39270020, 2024). "Mice treated with 20 mg·kg−1 of LAT9997 had more moderate lymphopenia and possessed significantly greater numbers of circulating B cells, CD4+ T cells, CD8+ T cells, and double-negative T cells." (PMID 38060822, 2024). "In patients with glioblastoma and lymphopenia after standard therapy, neither the total lymphocyte count nor CD4+ cell recovery was augmented by the reinfusion of autologous lymphocytes harvested using apheresis prior to therapy." (PMID 38390330, 2024). "CIBERSORT-derived proportional cell estimates from both classifiers show that neutrophils and CD4+\CD8+ T cells are positively and negatively correlated to PC1, respectively, consistent with neutrophilia and lymphopenia reported previously for sepsis subjects 17,18." (PMID 38816375, 2024). "To this end, we performed whole exome sequencing and functional immune assessment in a previously healthy Asian female, who experienced severe respiratory failure due to Pneumocystis jiroveci pneumonia and non-HIV-related CD4 lymphocytopenia." (PMID 39224595, 2024). "In both forms of APDS, CD4+ T-cell lymphopenia is a result of reduced naïve CD4+ T cells, while no change in naïve CD4+ T cells is identified in APDS-L, differentiating it from APDS1 and APDS2." (PMID 39679264, 2024). "Furthermore, their blood test with lymphopenia, BALF with decreased CD4/CD8 ratio, and increased neutralizing antibody titer suggested that CD4 T-cell responses are associated with more efficient viral clearance in immunocompromised patients." (PMID 39723265, 2024). "Patients with complicated myocarditis requiring vasopressors tended to exhibit more CD8+ T-cell lymphopenia compared with those with uncomplicated myocarditis who did not require vasopressors (CD4+/CD8+ T-cell ratio: 2.9 in vs. 2.0; p = 0.29)." (PMID 38398340, 2024).
lymphopenia (continued). "A variety of immunodeficiencies are seen in patients with GS like low to total absence of peripheral B cells with hypogammaglobulinemia, variably altered T-cell populations, CD4/CD8 ratio reversal, CD4 lymphopenia, and variable proliferative response to mitogen." (PMID 39246613, 2024). "This was also confirmed in another study where they concluded that in infection with SARS-CoV-2, lymphocytopenia is a significant feature and that CD8+ and CD4+ T cells are overactivated, as demonstrated by the expression of HLA-DR/CD38 resulting in dysregulation of NAD+ metabolism." (PMID 36675642, 2023). "Persistent infection with BVDV is the result of immune tolerance and is not usually associated with lymphopenia, but acute BVDV infection results in systemic immunosuppression characterised by depletion of circulating lymphocytes and CD4+ and CD8+ T cells." (PMID 37376677, 2023). "Our findings highlight that CD4+ T, CD8+ T, and CD19+ B cells, which play crucial roles in the immune response, may be the primary cell types affected by this lymphopenia." (PMID 38088961, 2023). "As our results indicate that AD development in IL-7 KO NC mice is accompanied by a decreased number of CD4+ and CD8+ T cells, it would be worthwhile to investigate whether IL-7 is related to the onset of lymphopenia in AD patients." (PMID 37373104, 2023). "We found a mild lymphopenia (<1.2 × 103 lymphocytes per μL) in non-infected HD patients compared to HC, mainly due to reduced helper CD4+ T (Th) cell counts." (PMID 36675231, 2023). "A decrease in the number of CD4+ and CD8+ cells also characterizes lymphopenia." (PMID 37377785, 2023). "Although the definite mechanism of lymphopenia has not been determined, decreased numbers of CD4- and CD8-positive T cells or defects in proliferation and differentiation of T cells are presumed relevant." (PMID 36676741, 2023). "This phenomenon is supported by the theory that the T lymphocyte cells (including CD4 and CD8 cells) might be killed by viruses such as influenza in severe cases and result in profound lymphopenia." (PMID 37441773, 2023). "Second, we did not assess the possible degree of peripheral lymphopenia and characterize in detail the different response of CD4+ and CD8+ T-cells." (PMID 36757971, 2023). "Over time, lymphopenia progresses with age, affecting CD8+ and CD4+ T cells." (PMID 36960048, 2023). "Within the adaptive immune compartment, global T and B cell lymphopenia predominated in critically ill patients, with the remaining T cell pool enriched with PD-1+ CD4+ and CD8+ T cell clusters (CD4-2, CD4-3 and CD8-6) and regulatory T (Treg) cell (CD4+CD25+FoxP3+, CD4-4) clusters." (PMID 36894652, 2023). "High levels of miR-34a-5p in naïve CD4+ T cells inhibit Th1 cell polarization by down-regulating CXCR3, leading to the diminished activation of cytotoxic T lymphocytes, natural killer cells, and natural killer T cells, as well as possible lymphopenia." (PMID 37509488, 2023). "Here, we report a case of disseminated NTM infection in a patient with neutralizing antibodies to IFN-γ, in addition to idiopathic CD4 lymphocytopenia, but with no previous immunodeficiency." (PMID 36717786, 2023). "Cases showed a higher prevalence of high-dose steroid therapy and lymphopenia with CD4+ < 200/μL, primarily due to SARS-CoV-2 infection and not related to underlying comorbidities." (PMID 36675909, 2023). "show that of 11 uninfected CVID-patients with no lymphopenia, seven had reactive CD4+ T-cells against SARS-CoV-2 spike proteins but none against nucleocapsid protein." (PMID 37180118, 2023). "Previous studies described an inversion of the CD4/CD8 ratio, a more pronounced decrease of effector and naïve T-cells compared with cells of a memory phenotype, and a prolonged T-cell dysfunction and reported a more severe and sustained lymphopenia." (PMID 35281040, 2022).
lymphopenia (continued). "Remarkably, CD4+ and CD8+ T cells accumulated in the BM after CLP and led to a three-fold increased T cell number (in comparison with sham treatment) by 24 h after sepsis induction that is in contrast to lymphopenia in the spleen." (PMID 36148245, 2022). "Furthermore, severely-lymphopenic patients, at diagnosis, had a significantly lower number of CD3 + CD4 + /CD45 + and CD16 + CD56 + /CD45 + cells, as compared to patients with moderate lymphopenia." (PMID 35486145, 2022). "Attempts have been made to understand the role of antifungal CD8+ T cells in the absence of CD4+ T cells, a potential avenue to exploit residual immunity for preventive and therapeutic purposes for individuals with CD4+ T-cell lymphopenia." (PMID 36177012, 2022). "We propose that toxic solutes from the gut bacterial flora may impair CD4+ T cell recovery during ART and may contribute to CD4+ T cell lymphopenia characteristic of INRs." (PMID 35316209, 2022). "In the presence of lymphopenia, the results obtained from immune marker tests, such as total immunoglobulin levels or the CD4 count, are not reliable; therefore, these tests were not performed." (PMID 35632677, 2022). "Consistent with previous studies, we observed significant lymphopenia in SLE patients compared with HC and significant decrease in all lymphocyte subpopulations (including CD4+ T cells, CD8+ T cells, DN T cells, B cells, NK cells and DC), validating our technical approach." (PMID 35603218, 2022). "In this study, changes such as a significant increase in the number of CD4+ and CD8+ T cells were observed, which led to a decrease in lymphopenia in patients, as well as a significant reduction in all acute inflammatory factors of serum and optimal improvement of pulmonary inflammation in patients." (PMID 35255966, 2022). "The low number of CD8 cells was not accompanied by CD4 lymphopenia, as shown by the decreased CD8/CD4 ratio in the spleen (7.7) and MLN (2.6, n=3) of Srsf1-cKO mice compared to WT mice (1.3 and 0.96, p=0.0009 and p<0.0001, respectively)." (PMID 36189299, 2022). "Of interest to our hypothesis, similar to the inflammatory marker changes, the changes in absolute numbers of CD4 and CD8 between HIV+ and HIV were less significant in the older age group, probably due to the overall age‐related lymphopenia." (PMID 35975357, 2022). "A significant increase in spike-specific CD4+ T cells was observed by AIM in all postvaccination groups apart from the S1P receptor modulators cohort, likely due to the pronounced S1P-mediated CD4+ T cell lymphopenia." (PMID 35030101, 2022). "Neither CD4+ T cell lymphopenia nor increase of effector memory population (CD62L− CD44high) were observed in the spleens of naïve 6-week-old T-Atg7−/− OT-II mice." (PMID 36055998, 2022). "Likewise, the most pronounced changes in lymphocyte counts were evident in MM patients with lymphopenia, demonstrated by diminished overall CD3+ T cells, CD4+ T helper cells and CD19+ B cells." (PMID 35634285, 2022). "The prevalence of CD4+ and CD8+ T lymphopenia was similar in the study population (around 29%)." (PMID 35546670, 2022). "Three of these patients had normal CD3+ T cell counts, including 1 with B cell and CD4 lymphopenia, and the fourth had non-SCID TCL due to partial DiGeorge syndrome." (PMID 34539671, 2021). "Patients with total, CD3, and CD4 lymphopenia were more likely to have higher saliva viral load, but not NPS viral load." (PMID 33467982, 2021). "In addition, lymphopenias in CD8+ T cells and CD4+ T cells are common and correlate with disease severity." (PMID 33498725, 2021). "Furthermore, in animals, it has been demonstrated that CD4+ and CD8+ T-cell lymphopenia exists in the spleens of aged Balb/c mice." (PMID 33923792, 2021). "Moderate CD4+- and severe CD8+-T-lymphopenia were present in P1." (PMID 34080085, 2021).